IL17A (interleukin 17A)
Diseases named in the same sentence as IL17A in open-access papers (continued):
Sharing a sentence is not in itself a finding about the gene and the disease.
psoriasis (continued). "The compounds suppressed the expression of IL-12/IL-23 p40, IL-17A, IL-22 and IL-23 p19 in vitro, and in vivo they ameliorated psoriasis-like skin lesions, decreased IL-17A mRNA expression, and increased the expression of keratinocyte differentiation markers." (PMID 30544700, 2018). "Increases in CD8+ T cell derived TNF-α and IL-17A also intriguing as psoriasis has traditionally been thought of as a Th1/Th17 mediated disease." (PMID 30054515, 2018). "Recently, however, there has been a paradigm shift in the understanding of cellular sources of IL-17A in psoriasis and PsA." (PMID 30109481, 2018). "Keratin 17 not only reflects the differentiation status of epidermal keratinocytes, but also participates in the pathogenesis of psoriasis by interacting with IL-17A and IL-2232." (PMID 30038329, 2018). "By IHC experiments using AF-317-NA, we too detected IL-17A+-neutrophils not only in skin sections of psoriasis patients but also in cytospin slides of neutrophils isolated from HDs and incubated for 3 h with or without R848, at similar levels." (PMID 29719541, 2018). "The importance of IL-17A in the pathogenesis of psoriasis has been well documented by genetic studies and data from experimental or animal models of psoriasis and skin tissue biopsy analysis." (PMID 29740348, 2018). "In line with the key role of IL-17A, the main gene variants associated with psoriasis outside the MHC locus are single nucleotide polymorphisms, belonging to the IL-23/IL-17A axis (IL23R, IL12B, and IL23A) and the NF-κB pathway (TNFAIP3)." (PMID 29971067, 2018). "This review will briefly debate the role of IL-17A as key effector molecule, retracing the key discoveries that led to the current understanding of psoriasis as an IL-17A driven disease." (PMID 30127781, 2018). "In a murine model of psoriasis, a subset of RORγt+ γδ T cells form resident-memory cells in skin that rapidly produce large amounts of IL-17A/F." (PMID 30109481, 2018). "Heatmaps of expression ratios and z-scores for the “Mitotic Roles of Polo-like Kinase”, “Cyclins and the Cell Cycle Regulation” and “Role of IL-17A in Psoriasis” pathways." (PMID 29871627, 2018). "Biologics targeting TNF-α and IL-17A have been developed and found to be very effective for managing psoriasis." (PMID 30321197, 2018). "WCR significantly ameliorated development of IMQ-induced psoriasis-like dermatitis and reduced levels of Th17 cytokines (IL-17A, IL-22, and IL-23) in both serum and dorsal skin." (PMID 29619073, 2018). "We here demonstrate unique effects of IL-36 in epidermal KCs and functional associations between IL-36 and other cytokines validated as psoriasis drug targets (i.e., TNF, IL-17A, and IL-23)." (PMID 29434599, 2018). "In this study, we analyzed the potential involvement of IL-38 in psoriasis by evaluating its circulating and skin levels in affected patients before and after the biological inhibition of IL-17A with secukinumab." (PMID 30377293, 2018). "Among them, fully human monoclonal antibody secukinumab (Cosentyx), a product of Novartis International AG, targeting human IL-17A cytokine, is available for treatment of psoriasis, ankylosing spondylitis, and psoriatic arthritis." (PMID 30304852, 2018). "The inhibition of autophagy via activation of PI3K/AKT/mTOR has been suggested as a therapeutic method for the treatment of IL-17a-mediated psoriasis." (PMID 30108582, 2018). "Multiple cytokine signaling pathways involved in the pathogenesis of psoriasis, including IL-1, IL-6, IL-17A and interferon signaling, were enriched in the current analysis." (PMID 29871627, 2018). "We thus focussed our review on the diseases where IL-17A has proven to be a key player, i.e., RA, psoriasis, CD, and MS." (PMID 29740348, 2018). "TH17 cytokines, such as IL-17A, IL-17F, and IL-22, represent the key effector cytokines in psoriasis pathogenesis as they directly drive the development of a psoriatic phenotype." (PMID 30555460, 2018).
psoriasis (continued). "CD11b+F4/80+macrophages sorted from skin tissue with IMQ-induced psoriasis-like dermatitis expressed high levels of IL-17A and IL-22 molecules." (PMID 29508278, 2018). "The shift towards a Th1 dominated cytokine profile is supported by elevated TNF-α and IL-17A production from CD4+ T effector cells in psoriasis samples." (PMID 30054515, 2018). "GSEA also highlighted the presence of a psoriasis gene signature in the IL-17A/TNF-treated cells which was suppressed by treatment with rhodomyrtone." (PMID 30321197, 2018). "The centrality of IL-23 and IL-17A to psoriasis and PsA pathogenesis has resulted in many new biologic therapies targeting these cytokines." (PMID 30109481, 2018). "The idea that psoriasis is purely a Th17 cell-dependent disease is thus replaced by the concept of psoriasis as an IL-17A-driven disease." (PMID 30127781, 2018). "Vγ4 T cells also produce IL-17A to induce psoriasis-like skin inflammation, and IL-17A-positive T cells expand promptly in draining lymph nodes when exposed to the inflammatory agent imiquimod." (PMID 29915573, 2018). "IL-17A and IL-22 have similar pathological effects in inflammatory diseases, such as psoriasis and arthritis." (PMID 29401501, 2018). "Effects of TNF-α inhibition in psoriasis and PsA are complex, because therapeutic benefits likely result from indirect adaptive immune effects on the IL-23/IL-17A axis." (PMID 30109481, 2018). "Stressing the importance of IL-17A, these therapies represent the most effective approach to treat psoriasis so far." (PMID 30127781, 2018). "CD4+CD25+Foxp3+ Tregs can differentiate into IL-17A-producing Th17 cells in patients with psoriasis." (PMID 30258447, 2018). "“Role of IL-17A in psoriasis” ranked high in both signatures, supporting its role in both populations studied." (PMID 28865459, 2017). "In human IL-17A-related skin diseases, such as psoriasis and AD, CD206 is a specific marker for mature macrophages in the skin." (PMID 28963556, 2017). "Among the investigated key cytokines relevant in psoriasis, IFNγ was detected as the main inducing factor for inflammatory caspase-5 besides caspase-1 in keratinocytes, whereas IL-17A had an amplifying effect." (PMID 28422993, 2017). "It is expressed by keratinocytes and together with IL-17A and IL-17F is involved in the pathology of psoriasis." (PMID 28590443, 2017). "IL-17A has been implicated in chronic inflammatory and autoimmune diseases, and anti-IL-17A antibodies have shown remarkable clinical efficacy in psoriasis and psoriatic arthritis patients." (PMID 28827714, 2017). "It is strongly suggested that sbC-PEGylation is a useful method for developing therapeutic anti-IL-17A aptamers for systemic inflammatory diseases, such as psoriasis and AS." (PMID 27827561, 2017). "Clinical studies have shown that neutralizing tumor necrosis factor-alpha (TNF-α), interleukin (IL)-12/23, or IL-17A is efficacious, demonstrating the central role of Th1/Th17 cells in psoriasis pathogenesis." (PMID 28865459, 2017). "To confirm the contribution of IL-17A in the exacerbated skin inflammation in HFD-fed mice, we applied IL-17A-deficient mice to the HFD-induced obese model and then to the IMQ-induced psoriasis model." (PMID 29074858, 2017). "Due to previous preclinical data and its proven efficacy in psoriasis and psoriatic arthritis, a number of monoclonal antibodies have been developed to target IL-17A in SpA." (PMID 28149838, 2017). "Like IL-17A, IL-17F has been ascribed a pro-inflammatory role in psoriasis, e.g., through induction of IL-6 and IL-8 in keratinocytes and regulation of CCL20 and human beta-defensin-2." (PMID 29104241, 2017). "The top 15 pathways included the “Role of IL-17A in psoriasis,” indicating that the IL-17 pathway is a key component of moderate psoriasis." (PMID 28865459, 2017).
psoriasis (continued). "In a mouse model of psoriasis induced by topical application of Imiquimod, it was found that ILC3s are a cellular source of IL-17A and IL-22 that mediate the Imiquimod-induced psoriasis-like disease." (PMID 28271445, 2017). "Regarding the relevance of IL-17A in psoriasis, we investigated the caspase- mediated IL-1β activation by epidermal keratinocytes further." (PMID 28422993, 2017). "IL-8 and IL-17A contribute to the pathogenesis of psoriasis by inducing keratinocyte proliferation and are present at increased levels in the skin and circulation of psoriasis patients." (PMID 28723914, 2017). "Similar to the results reported for protein secretion, an increase in mRNA levels of genes related to Th17 and Th1 responses in psoriasis IL-17A, IL-22, IL-23p19, RORγt, and IL-12p40 was observed in IMQ-treated group." (PMID 28761880, 2017). "In recent clinical trials, antibodies targeting IL-17A and IL-17Ra have demonstrated remarkable efficacy in psoriasis patients." (PMID 28672038, 2017). "The pathway “Role of IL-17A in psoriasis” ranked even higher in this analysis than in the disease signature, and all pathway genes were reversely regulated." (PMID 28865459, 2017). "Gene expression profiles of the lesional psoriasis have established that psoriasis is mainly induced by IL-23 and type 17 (IL-17A, IL-17F, and IL-22) cytokines." (PMID 29295520, 2017). "IL-22 and IL-17F cellular sources in psoriasis have been less studied and possibly assumed to be closely co-regulated with IL-17A." (PMID 28790368, 2017). "As the key cytokines in the pathogenesis of psoriasis, IL-17A can synergize with TNF-α to induce the production of MCP-1, IL-8, and MMP-1 by dermal fibroblasts." (PMID 28217129, 2017). "RORγt compound can selectively regulate Th17 signature gene expression in mononuclear cells isolated from both the blood and affected skin of psoriasis patients and inhibited IL-23 induced IL-17A from psoriasis patient PBMC." (PMID 28763457, 2017). "In B6 mice, IMQ increased expression of Il17a, Il17b, Il17c, and Il17f, partially consistent with human psoriasis, but in the BALB/c strain such genes were unaltered by IMQ." (PMID 28279190, 2017). "Psoriasis is a chronic inflammatory skin disease characterized by increased infiltration of IFNγ-producing Th1 cells as well as IL-17A-producing Th17 cells in the lesional plaques." (PMID 28472186, 2017). "The human monoclonal antibodies ixekizumab and secukizumab are members of the class of psoriasis drugs that target IL-17A." (PMID 28894754, 2017). "Secukinumab, a fully human monoclonal antibody that selectively neutralizes interleukin-17A (IL-17A), has been shown to have significant efficacy in the treatment of moderate to severe psoriasis, psoriatic arthritis and ankylosing spondylitis." (PMID 28868144, 2017). "The central role of IL-17 in psoriasis is most vividly documented by the success of Secukinumab, a fully human monoclonal antibody, which selectively targets IL-17A." (PMID 29142248, 2017). "Antibodies targeting IL-17A and the IL-17 receptor IL-17RA have shown clinical efficacy in psoriasis, rheumatoid arthritis, and uveitis." (PMID 28763457, 2017). "It has also been reported that human anti-IL-17A antibody can effectively treat psoriasis during clinical trials, which confirms that the IL-17/IL-23 axis is a good target for psoriasis treatment." (PMID 29138509, 2017). "Recently, the novel biologic agents that specifically target IL-17A and the p40 subunit of IL-12 and IL-23 have been used effectively in the treatment of psoriasis." (PMID 28900461, 2017). "Among them, IL-17A is a key molecule for amplifying inflammation in psoriasis through the propagation of the production of various proinflammatory cytokines and chemokines." (PMID 29232931, 2017).
psoriasis (continued). "This NMA includes the newly licensed anti-IL-17A monoclonal antibody, ixekizumab, and considers joint rankings of multiple outcomes for psoriasis, including DLQI, and to provide absolute effect estimates to help inform clinical decision making." (PMID 28457908, 2017). "Then, we proved mS100a7a15, mature IL-1α and calpain-1 were highly expressed in imquimod-induced psoriasis model and mouse IL-17a-neutralizing antibody treatment attenuated mS100a7a15 expression." (PMID 28060905, 2017). "Secukinumab was the first IL-17A inhibitor approved in 2015 for treatment of patients with psoriasis, and about one year later secukinumab was also approved for PsA." (PMID 29104241, 2017). "The γδ T cells in the skin-draining lymph node of psoriasis produce approximately 10 times more IL-17A and IL-22 than CD4 T cells." (PMID 28761880, 2017). "Most of the increased-γδ T cell subset was Vγ4+ γδ T cells, which is one of the main IL-17A-producing cell subset in the IMQ-induced psoriasis model." (PMID 29074858, 2017). "Th17-derived IL17A and IL17F are linked to the pathogenesis of some autoimmune diseases, including multiple sclerosis, rheumatoid arthritis, psoriasis, and Grave’s disease." (PMID 28430123, 2017). "Oral administration of resveratrol diminished the severity of imiquimod-induced psoriasis-like inflammation in an animal model, and microarray analysis revealed that resveratrol treatment inhibited imiquimod-induced expression of IL-17A, IL-19, and IL-23p19." (PMID 28894754, 2017). "IL-17A is a key cytokine for the development of psoriasis; however, an alternative pathway has been reported in the development of IMQ-induced psoriatic dermatitis in the absence of IL-17 receptor signaling." (PMID 29074858, 2017). "Once Th17 cells are activated, they produce many mediators, including IL-17A and IL-22 which consequently induce proliferation of keratinocytes and other clinical symptoms of psoriasis." (PMID 28900461, 2017). "Among these subpopulations, NKp44+ ILC3 were reported to contribute to the pathogenesis of psoriasis, since IL-17A- and IL-22-producing NKp44+ ILC3 were increased in both the peripheral blood and the skin of patients with psoriasis." (PMID 27158469, 2016). "Within these, dermal and epidermal γδ T cells can be distinguished whereas the main producers of IL-17A in IMQ-induced psoriasis are the dermal γδ T cells." (PMID 26999594, 2016). "The IL-17A covalent homodimer’s significance in psoriasis is evidenced by the recent success of anti-IL-17A biologics as therapeutics." (PMID 27527709, 2016). "In conclusion, IL17A is elevated in lesional skin from psoriasis patients and plays crucial role in disease severity." (PMID 28042206, 2016). "We herein describe a previously unidentified mode of action of IL-17A potentially opening new avenues for the treatment of psoriasis." (PMID 26781963, 2016). "Mice, that spontaneously develop psoriasis-like disease based on IL-17A overexpression in the skin (K14-IL-17Aind/+), show at least a partial remission of disease after anti-IL-6 treatment." (PMID 26999594, 2016). "IL17A plays a pivotal role in psoriasis pathogenesis, and its antagonists show great efficacy in moderate-severe psoriasis patients." (PMID 27089880, 2016). "IL-17A is a central driver in disease pathogenesis; hence, IL-17 inhibitors have been extensively researched for the treatment of psoriasis." (PMID 26573299, 2016). "Th17 cells and the cytokines secreted by them, such as IL-17A, IL-17 F, IL-22 and IL-21, play a role in numerous chronic inflammatory diseases including psoriasis." (PMID 27581210, 2016). "Nonetheless, the peak ratios are observed for the Role of Il17F in inflammatory diseases and the role of Il17A in psoriasis." (PMID 26932723, 2016). "Antibodies targeting IL-17A or its receptor IL-17RA show unprecedented efficacy in the treatment of autoimmune diseases such as psoriasis." (PMID 27853279, 2016).
psoriasis (continued). "In psoriasis the protein mediates the expression of psoriasin induced by IL-17A via ERK-Egr-1 pathway." (PMID 26966903, 2016). "Recently, we demonstrated that IL-17A, IL-22, and IL-6 cytokines were more elevated in serum from psoriasis patients than in heathy controls." (PMID 28042206, 2016). "In this mouse model the cytokine IL-17A is specifically overexpressed in keratinocytes, resulting in a strong psoriasis-like phenotype." (PMID 26999594, 2016). "The antibody drugs that neutralize IL-23 or IL-17A have shown a significant efficacy in the treatment of psoriasis." (PMID 27149476, 2016). "Although the pathogenesis of psoriasis is not fully understood, evidence suggests that many cytokines, including IL-6, IL-17A, IL17F, IL-22, IL-23 and TNF-α, are involved and interact as a network in the pathogenesis of psoriasis." (PMID 27581210, 2016). "The importance of IL-17A in IMQ-induced psoriasis-like skin disease is undisputed and the main producers of IL-17A in this model are γδ T cells." (PMID 26999594, 2016). "Comparison between NLP and C samples found up-regulation of canonical pathway “Role of IL-17A in Psoriasis” (p = 2.31E-08)." (PMID 25897967, 2015). "Of the most psoriasis-specific DEGPs, the majority were induced by IL-17A (e.g., FERMT1, GLUL, SULT2B1); in contrast, the most non-specific DEGPs were not disproportionately induced by IL-17A and several were repressed (e.g., AKR1B10, RNF213, ISG15)." (PMID 26251673, 2015). "IL-17A and IL-17RA are emerging as effective biologic targets for autoimmune conditions, particularly psoriasis." (PMID 25849644, 2015). "The response of psoriasis to antibodies targeting the interleukin (IL)-23/IL-17A pathway suggests a prominent role of T-helper type-17 (Th17) cells in this disease." (PMID 25828362, 2015). "More recently, Phase II and III clinical trials testing biologics that directly target IL-17A or IL-17RA have shown considerable promise in treating psoriasis, and are under evaluation for a number of other rheumatologic conditions." (PMID 25849644, 2015). "Within psoriasis lesions, IL-17A is thought to be produced by Th17 cells, γδ T-cells, neutrophils, mast cells, and innate lymphoid cells." (PMID 25883770, 2015). "Consistent with this concept, IL-23 (believed to mediate the crosstalk between dendritic and Th17 cells) and IL-17A (a key effector cytokine released from Th17 cells) have emerged as attractive targets for the development of new therapies for psoriasis." (PMID 25828362, 2015). "Th17 cells synthesize IL-17A, IL-17F, IL-21, and so forth and have been demonstrated in autoimmune disease such as Sjögren's syndrome, multiple sclerosis, psoriasis, autoimmune uveitis, juvenile diabetes, rheumatoid arthritis, and Crohn's disease." (PMID 26078981, 2015). "Quantitative PCR confirmed a resveratrol dependent decrease in mRNA levels of IL-17A and IL-19; both central in developing psoriasis." (PMID 25965695, 2015). "In an earlier study of apremilast, decreases in IL-17A were linked to decreased keratinocyte proliferation and to PASI-75 response in patients with recalcitrant psoriasis." (PMID 25973439, 2015). "In contrast, genes induced by IL-17A (or IL-17A plus TNF) in cultured KCs tend to be more psoriasis-specific and less commonly elevated in other skin conditions." (PMID 26251673, 2015). "IL-17A not only contributes to the epidermal abnormalities typical of psoriasis, but also induces the expression of chemokines in keratinocytes such as GRO-α (CXCL1) and IL-8 (CXCL8), which orchestrate the recruitment of neutrophils to psoriatic lesions." (PMID 25828362, 2015). "We also uncovered “psoriasis response elements” (PREs) overrepresented in psoriasis DEG promoter regions, which are present within enhancers near cytokine-encoding genes (e.g., IL17A, IL19 and IL1B)." (PMID 25883770, 2015). "Human mucosal Foxp3+Tregs express IL-17A in inflammatory conditions, such as periodontitis, psoriasis and IBD." (PMID 25790134, 2015).